BRD2 (bromodomain containing 2)
Description:
Chromatin reader protein that specifically recognizes and binds histone H4 acetylated at 'Lys-5' and 'Lys-12' (H4K5ac and H4K12ac, respectively), thereby controlling gene expression and remodeling chromatin structures. Recruits transcription factors and coactivators to target gene sites, and activates RNA polymerase II machinery for transcriptional elongation. Plays a key role in genome compartmentalization via its association with CTCF and cohesin: recruited to chromatin by CTCF and promotes formation of topologically associating domains (TADs) via its ability to bind acetylated histones, contributing to CTCF boundary formation and enhancer insulation. Also recognizes and binds acetylated non-histone proteins, such as STAT3. Involved in inflammatory response by regulating differentiation of naive CD4(+) T-cells into T-helper Th17: recognizes and binds STAT3 acetylated at 'Lys-87', promoting STAT3 recruitment to chromatin. In addition to acetylated lysines, also recognizes and binds lysine residues on histones that are both methylated and acetylated on the same side chain to form N6-acetyl-N6-methyllysine (Kacme), an epigenetic mark of active chromatin associated with increased transcriptional initiation. Specifically binds histone H4 acetyl-methylated at 'Lys-5' and 'Lys-12' (H4K5acme and H4K12acme, respectively).
Synonyms: KIAA9001; RING3; D6S113E; NAT; FSHRG1; BRD2-IT1; FSH; FSRG1; O27.1.1; RNF3
Tractability: Small molecule: a drug acting on it is in phase 2 or 3 trials; a structure with a bound ligand is known; a high-quality ligand is known; it has a binding pocket of medium quality; it belongs to a druggable protein family. PROTAC: it is named in the literature on targeted protein degradation; ubiquitination databases record sites on it; its protein half-life has been measured; a small molecule that binds it is known.
Target class: Epigenetic regulator; Bromodomain; Reader
Chemical probes: (+)-JQ1 (high quality), ABBV-744 (high quality), AZD-5153 (high quality), GSK046 (high quality), GSK620 (high quality), GSK789 (high quality), GSK973 (high quality), I-BET151 (high quality), MT1 (high quality), MZ1 (high quality), MZP-54 (high quality), PFI-1 (high quality), Pelabresib anhydrous (high quality), biBET (high quality), bromosporine (high quality), iBET-BD1 (high quality)
Gene: Protein-coding gene on chromosome 6 (32,968,594 to 32,981,505, forward strand). Ensembl gene ENSG00000204256.
Subcellular location: Nucleus; Chromosome
Subcellular location (Human Protein Atlas): Nuclear speckles; Nucleoplasm
Pathways (Reactome):
Gene expression (Transcription): RUNX3 regulates p14-ARF
Gene Ontology:
Molecular function: acetylation-dependent protein binding; histone H3K14ac reader activity; histone H4K12ac reader activity; histone H4K5ac reader activity; protein binding; protein serine/threonine kinase activity; chromatin binding
Biological process: chromatin looping; positive regulation of T-helper 17 cell lineage commitment; protein localization to chromatin; regulation of transcription by RNA polymerase II; transcription elongation-coupled chromatin remodeling; spermatogenesis; regulation of DNA-templated transcription
Cellular component: chromatin; chromosome; nuclear speck; nucleoplasm; nucleus
Genetic constraint (gnomAD): Loss-of-function variants: 15 observed, 82.49 expected, observed/expected ratio (o/e) 0.18, 90% interval 0.12 to 0.28. The synonymous counts are far from expectation, so gnomAD's model fits this gene poorly and the ratio says little. Missense variants: 1,053 observed, 1,040.9 expected, observed/expected ratio (o/e) 1.01, 90% interval 0.96 to 1.06. Synonymous variants: 488 observed, 378.15 expected, observed/expected ratio (o/e) 1.29, 90% interval 1.2 to 1.39.
Homologues: Orthologues: chimpanzee BRD2 (99% identical), macaque BRD2 (99% identical), dog BRD2 (98% identical), pig BRD2 (98% identical), rabbit BRD2 (97% identical), rat Brd2 (96% identical), guinea pig BRD2 (96% identical), mouse Brd2 (96% identical), tropical clawed frog brd2 (72% identical), zebrafish brd2a (63% identical), zebrafish brd2b (19% identical), Drosophila melanogaster tbrd-1 (19% identical). Paralogues in human: BRD3 (58% identical), BRD4 (53% identical), BRDT (45% identical), CECR2 (19% identical), BPTF (19% identical), BAZ2B (15% identical), BAZ2A (14% identical), BAZ1B (13% identical), BAZ1A (11% identical), KAT2B (10% identical), KAT2A (9% identical).
Diseases named in the same sentence as BRD2 in open-access papers:
BRD2 is named in the same sentence as 134 diseases in open-access papers, as found by Europe PMC text mining. Sharing a sentence is not in itself a finding about the gene and the disease. The quoted sentences say what the papers report.
melanoma (22 papers, 2015 to 2025). A malignant, usually aggressive tumor composed of atypical, neoplastic melanocytes. "In melanoma, glioma, ovarian cancer, and some other cancers, the overexpression of BRD2 and BRD4 is associated with poor prognosis, and their presence affects the pathways of nuclear factor-κB (NF-κB), Notch, and Hedgehog (Hh) signaling." (PMID 34540687, 2021). "In melanoma, BRD2 interacts with the histone variant H2A.Z.2, leading to upregulation of cell cycle genes and proliferation." (PMID 29650805, 2018). "Interestingly, apart from acetylated histone, selective BRD2 recruitment has shown to be mediated by a histone variant H2A.Z.2, a driver of malignant melanoma to promote melanoma cell survival." (PMID 34540900, 2021). "I-BET151 inhibits NF-kB activation in melanoma by targeting BRD2, causing cycle arrest, promoting apoptosis, and inhibiting the production of cytokines (e.g., IL6 and IL-8) and chemokines (e.g., CXCL10 and CCL5), which indicates that I-BET151 may have a therapeutic effect on melanoma." (PMID 34540687, 2021). "It was postulated that H2A.Z.2 promote proliferation of melanoma cells by recruitment of Bromodomain-containing protein 2 (BRD2) and E2F1 to the promoter region of E2F target genes, where H2A.Z is known to occupy." (PMID 38542118, 2024). "Previously, it was demonstrated that H2AZ2 recruits E2F1 and BRD2 to the promoters of cell cycle genes to drive melanoma proliferation and invasiveness." (PMID 35058574, 2022). "Examinations of Human Protein Atlas datasets revealed that overexpression of BET family BRD proteins (i.e., BRD2 and BRD3), BRD9, BRD7, and EZH2 were associated with relatively poor three-year survival in melanoma patients." (PMID 34771678, 2021). "The authors showed that AMIGO2 is regulated by a melanoma-specific BRD2/4-bound promoter and super-enhancer configuration." (PMID 32042336, 2020). "In melanoma, H2A.Z.2 is incorporated at E2F-target, cell cycle-promoting genes and mediates their overexpression, in cooperation with bromodomain-containing protein 2 (BRD2)." (PMID 33167489, 2020). "Key recent studies have shown that JQ1 treatment in melanoma and multiple myeloma cells depletes BRD2 and BRD4 from promoter and enhancer regions of the genome, and this was associated with the disruption of transcriptional programs in these cells." (PMID 32315290, 2020). "In particular, the H2A.Z isoform H2A.Z.2 is highly expressed in melanoma and increases cell proliferation by recruiting BRD2 and E2F1 to E2F target genes." (PMID 32831131, 2020). "H2A.Z.2 is highly expressed in melanoma and is bound by and stabilizes histone reader protein BRD2, leading to activation of genes, especially E2F targets that promote cell cycle progression." (PMID 26426052, 2015). "In stage III melanoma patients, expression of BRD2/4 was strongly correlated with ErbB3." (PMID 31932756, 2020). "BRD2 together with E2F1 bind to E2F target genes in a H2A.Z.2-deposition dependent manner, in turn promote proliferation of melanoma cells." (PMID 38542118, 2024). "Previous studies have reported that BRD2 and BRD4 are overexpressed in melanoma tissues and are essential for tumor maintenance." (PMID 37513949, 2023). "BRD2 and BRD4 are overexpressed in human primary and metastatic melanomas, and their inhibition results in downregulation of IL-6 and IL-8." (PMID 36711038, 2023). "The silencing of BRD2 and BRD4, as well as treatment with BET inhibitors (BETis), can hinder the growth of melanoma." (PMID 37513949, 2023). "In melanoma, it was proposed that H2AZ2 exerts its oncogenic function by recruiting E2F1 and BRD2 to the promoters of cell cycle genes." (PMID 35058574, 2022). "Our analysis of publicly available Talantov melanoma datasets revealed that only EZH2, BRD7/9, BRD2/3/4, BRPF1, EHMT2, and KDM6B were significantly overexpressed at the mRNA level in patient melanoma tissue samples as compared to the normal skin samples." (PMID 34771678, 2021).
melanoma (continued). "There are at least two BET proteins in melanoma, in this case BRD2 and BRD4, that are documented to be overexpressed during melanoma progression." (PMID 34575678, 2021). "JQ1, which targets the BET family of BRD proteins (which includes BRD2, BRD3, and BRD4), effectively inhibited the growth of both the melanoma cell lines even at the lower concentrations." (PMID 34771678, 2021). "Gene expression and IHC analysis of human tissue biopsies have confirmed higher levels of BRD2 and BRD4 in primary and metastatic tumors relative to melanocytes and nevi, suggesting that these BET proteins are involved in melanoma tumorigenesis." (PMID 34575678, 2021). "Consistent with the ChIP-seq data showing overlapping peaks in human melanocytes and melanoma cells, we found that both BRD4 and BRD2 were bound to the Tyr and Tyrp1 promoters in Melb-a cells and that (+)JQ1 disrupted binding." (PMID 32151278, 2020). "BET protein consists of BRDT, BRD2, BRD3, and BRD4, among which BRD4 is mainly involved in melanoma progression." (PMID 33052224, 2020). "Among this family, it has been shown that BRD2 and BRD4 are overexpressed in melanoma tissues and are required for tumor maintenance by controlling the expression of key cell cycle and survival genes." (PMID 32042336, 2020). "Strikingly, H2A.Z.2 was shown to promote and/or maintain BRD2, E2F1 and histone acetylation levels in malignant melanoma." (PMID 31200754, 2019). "H2A.Z.2 recruits BRD2 and E2Fs, along with HAT activity, to promoters of E2F target genes in melanoma cells, facilitating expression of cell cycle genes and, ultimately, promoting cell proliferation." (PMID 31200754, 2019). "BET family members BRD2 and BRD4 are over expressed in melanoma and are able to be inhibited by a number of relatively novel drugs such as JQ-1 and I-BET151, leading to reduced melanoma growth, cell death and reduction in NF-κB activity." (PMID 26426052, 2015). "BET proteins bind acetylated lysines on histone H3 and H4 and recruit RNA polymerase II to drive transcription and two BET proteins—BRD2 and BRD4 are increased during melanoma progression." (PMID 26426052, 2015). "KDM6B, BRD2, and BRD3 were moderately to weakly expressed in melanoma samples, whereas weak staining intensity was observed for BRPF1 and EHMT2 in melanoma samples as compared with normal skin tissue indicating that they are significantly expressed at low levels in melanoma samples." (PMID 34771678, 2021). "Further, silencing of BRD2 or BRD3 did not change the effect of MZ1 on melanoma cell viability compared to control cells." (PMID 33958721, 2021). "BET protein involvement in melanomagenesis was demonstrated by Segura at al. when it was shown that BRD2 and BRD4 are overexpressed in human melanoma cell lines and tissues, controlling the expression of certain genes involved in cell cycle progressions and survival." (PMID 34575678, 2021). "Therefore, to mimic the clinical scenario, we conducted a long-term clonogenic survival assay using GSK343 (targeting EZH2), JQ1 (targeting BET family BRD proteins-BRD2 and BRD3), TP-472 (targeting BRD7/9) using multiple BRAF mutant melanoma cell lines (M14, SKMEL-28, A375, and A2058)." (PMID 34771678, 2021). "Another BETi, I-BET151, triggered the selective inhibition of the NF-κB signaling pathway in melanoma cells, regulating genes involved in inflammation (VEGF, CCL-20) and cell cycle progression (CDK6) and suppressing the production of IL-6 and IL-8 via BRD2 displacement." (PMID 34575678, 2021). "While it was possible to obtain overlapping BRD4, BRD2, and MITF peaks on representative genes in different melanocytes and melanoma cells, we could not find BRD4, BRD2, and MITF ChIP-seq data for the same melanocyte or melanoma cell line to reliably quantify the overlap." (PMID 32151278, 2020).
Obesity (16 papers, 2011 to 2025). Accumulation of substantial excess body fat. "The Brd2 (bromodomain containing 2) deficient model for “metabolically healthy” obesity has garnered attention recently and provides a novel interpretive tool." (PMID 37239458, 2023). "Obesity can also develop as results of gene disruption or deficiency, such as the Brd2 gene and the leptin gene, both leading to metabolic pathways towards an obesity-related phenotype." (PMID 34944474, 2021). "The knockout of BRD2 gene will cause obesity in mouse and HCRTR2 is a kind of orexin receptor, which plays a vital important role in feeding behavior and balance of energy metabolism." (PMID 31024621, 2019). "As c-Myc has close relationship with MEK/ERK signaling, we suggest that Brd2 and its associated protein complexes should be considered in cases of obesity-associated cancer." (PMID 24194944, 2013). "It has been reported that Brd2 disruption in mice causes severe obesity." (PMID 33830083, 2021). "In the Brd2 hypomorphic mice, severe obesity with lower blood glucose and enhanced glucose tolerance is due to a combination of hyperinsulinemia and marked reduction in macrophage infiltration into fat depot." (PMID 37961647, 2025). "Although disruption of BRD2 induced the development of severe obesity, knockout mice still presented with normal glycemia and glucose tolerance, and lower inflammation levels in their adipose tissues than control mice." (PMID 36015180, 2022). "On the other hand, disruption of Brd2 causes severe obesity in mice, although without Type 2 diabetes, however the obesity itself is a precipitating factor of many diseases, such as cancer." (PMID 24194944, 2013). "It is also important to note that the novel EC proteins, APP, CAD, BRD2 (which is part of DKFZp313H139), CST3, GRN, PPM1G and ZC3H4, have all been reported to be positively associated with obesity or adiposity, whilst the novel EC protein SLC25A24 may even prevent obesity and promote leanness." (PMID 37760635, 2023). "This may suggest that INS and BRD2 play an important role in BC patients with obesity." (PMID 37895140, 2023). "Therefore, regulation of the balance between BRD4 and BRD2 activities may inhibit metabolic diseases, such as obesity, type 2 diabetes, and related complications." (PMID 28931940, 2017). "Furthermore, disruption of Brd2 in mice causes severe obesity without type 2 diabetes." (PMID 24194944, 2013). "Obesity and low-grade inflammation induce insulin resistance but a recent study showed that TNF-α inhibited insulin-stimulated glucose uptake in 3T3-L1 cells, while knockdown of BRD2 maintained their insulin sensitivity." (PMID 36015180, 2022).
breast carcinoma (12 papers, 2016 to 2025). "In the studied MDA-MB-231 breast cancer cells, the transient silencing of BRD2/3/4 and bromodomain inhibition caused a significant increase in the mRNA of ABCC10, which is the most abundant MDR protein in this cell line." (PMID 34572840, 2021). "For example, BRD2 enhances epithelial-mesenchymal transition (EMT) in breast cancer cells, while BRD3 and BRD4 repress EMT." (PMID 37296612, 2023). "Consistent with previous reports, ZBC260 reduced breast cancer cell levels of BRD2, BRD3, and BRD4 proteins in a concentration-dependent manner." (PMID 37968653, 2023). "Additionally, higher BRD2 expression was significantly correlated with a detrimental prognosis in breast cancer and CRPC." (PMID 32927435, 2020). "However, more detailed studies are needed to elucidate the precise role of BRD2 in breast cancer." (PMID 31758045, 2019). "Furthermore, when comparing expression levels of BET proteins, we found that BRD2 showed higher expression levels compared to BRD3 and BRD4 in the three cell lines, suggesting that BRD2 could be a major target of (+)-JQ1 in canine mammary cancers." (PMID 31758045, 2019). "BRD2, a member of the bromodomain and extra-terminal (BET) family including mammalian BRD3, BRD4 and BRDT, is remarkably over-expressed in breast cancer, gastric cancer (GC), malignant pleural mesothelioma (MPM) and castration-resistant prostate cancer (CRPC)." (PMID 32927435, 2020). "To further investigate the role of JQ1 in AR expressing breast cancer cells, we assessed protein-protein interactions among ATAD2, AR, as well as JQ1 targets including BRD2, and BRD4." (PMID 31527644, 2019). "On the other hand, Brd2 and Brd3/4 activate independent transcriptional networks and thereby compete with one another to promote or repress, respectively, the epithelial to mesenchymal transition (EMT) in a breast cancer model." (PMID 34842711, 2021). "ABBV-744 did not significantly alter the levels of BRD2 or BRD3; however, a significant downregulation in BRD4 levels was evident at both 75 nM and 100 nM, indicating the potential selectivity of ABBV-744 towards BRD4 in ER+ breast cancer cells." (PMID 37627092, 2023).